ATF6 (activating transcription factor 6)
Diseases named in the same sentence as ATF6 in open-access papers (continued):
Sharing a sentence is not in itself a finding about the gene and the disease.
ischemic stroke (4 papers, 2015 to 2023). A stroke disorder caused by obstruction of blood flow to the brain, due to thrombotic (local blood clot formation) or embolic (due to a blood clot or other material traveling from another site) event. "Meanwhile, ischemic stroke also triggers ATF6 expression followed by ATF6 translocation into the Golgi apparatus." (PMID 37344501, 2023). "Collectively, we now have evidence that activation of ATF6 signaling improves outcomes in both transient and permanent ischemic stroke." (PMID 36313623, 2022). "As the ATF6 pathway has been increasingly considered a promising therapeutic target for ischemia-related diseases, we focused the current study on the ATF6 UPR branch in ischemic stroke." (PMID 36313623, 2022). "Here, we performed the first experimental study to demonstrate that activation of the ATF6 pathway improves not only the acute outcome but also long-term outcome after permanent ischemic stroke." (PMID 36313623, 2022). "Thus, rigorous preclinical studies are warranted to further evaluate the therapeutic potential of targeting the ATF6 pathway in ischemic stroke." (PMID 36313623, 2022). "Likewise, Yang’s research group used mice with the ATF6 pathway specifically activated in forebrain neurons to indicate the efficacy of ATF6 in improving ischemic stroke and CA outcomes, highlighting the specific roles of ATF6 in neuroprotection." (PMID 36506549, 2022). "However, the effect of ATF6 activation on the outcome after permanent ischemic stroke remains unknown." (PMID 36313623, 2022). "However, the effect of ATF6 activation on outcome after permanent ischemic stroke remains unknown." (PMID 36313623, 2022).
metabolic syndrome (4 papers, 2018 to 2023). A cluster of metabolic risk factors for CARDIOVASCULAR DISEASES and TYPE 2 DIABETES MELLITUS. "We show an upregulation of all three key sensors (PERK, ATF-6 and IRE1a) of the UPR pathway in Clec16aΔUBC mice with a picture of humanoid-like metabolic syndrome and autoimmunity, with potential implications for understanding mechanisms of weight reduction for future interventions." (PMID 33795715, 2021). "It was showed that under metabolic syndrome or T2D condition, hepatocytes abundantly accumulates unfolded or misfolded proteins in the ER lumen, which leads to the activation of three master regulators of ER stress, including protein IRE1α, PERK, and ATF6." (PMID 33808055, 2021).
Autoimmunity (3 papers, 2019 to 2024). The occurrence of an immune reaction against the organism's own cells or tissues. "In conclusion we propose that chronic ER stress mediated by ATF6 activation allows cell survival at the expense of minority MOMP-mediated mtDNA release, leading to the activation of the cGAS/STING pathway and type I IFN-stimulated gene induction predisposing to autoimmunity." (PMID 38378748, 2024).
Burkitt lymphoma (3 papers, 2010 to 2022). A rare form of malignant mature B-cell non-Hodgkin lymphoma. "In this study, we found that IRE1α/XBP1 axis inhibition exerted a stronger cytotoxic effect compared to the inhibition of the other two UPR sensors, namely PERK and ATF6, in Burkitt lymphoma (BL) cells, in correlation with c-Myc downregulation." (PMID 36012375, 2022). "Here, we show that the treatment of Burkitt lymphoma (BL) cells with verotoxin-1 (VT-1 or Stx1) consistently induced the ER stress response by activation of IRE1 and ATF6—two ER stress sensors—followed by increased expression of the transcription factor C/REB homologous protein (CHOP)." (PMID 32403276, 2020).
cardiac arrest (3 papers, 2019 to 2023). Cessation of breathing and/or cardiac function. "In agreement with such view, recent study documented neuroprotective impact of activation of ATF6 arm of UPR after cardiac arrest in mice." (PMID 37452223, 2023). "By contrast, ATF6 signaling remains a subject of debate: ATF6 expression was increased following MCAO in rats, but activation could not be demonstrated in an ischemia-reperfusion model by cardiac arrest in rats." (PMID 31275110, 2019).
cognitive decline (3 papers, 2018 to 2025). "Our results suggest that DREAM inhibition has a role in delaying cognitive decline in HD mice through a mechanism related to ATF6 processing." (PMID 29523177, 2018). "However, under chronic overload of the UPR pathway, ATF6 activation may contribute to cognitive decline and neuronal degeneration." (PMID 40806635, 2025). "To test whether a similar mechanism is involved in the partial protection from cognitive decline in repaglinide-treated HD mice, we analyzed the effect of repaglinide administration on ATF6 processing in R6/1 hippocampus, a brain area involved in learning and memory." (PMID 29523177, 2018).
Cognitive impairment (3 papers, 2018 to 2020). Abnormal cognition is characterized by deficits in thinking, reasoning, or remembering. "Recovery of ATF6 processing in the R6/1 hippocampus thus correlates with delayed cognition impairment after repaglinide administration." (PMID 29523177, 2018).
cystic fibrosis (3 papers, 2014 to 2016). Autosomal recessive disorder caused by pathogenic variants in the CFTR gene (cystic fibrosis transmembrane conductance regulator), which encodes a chloride and bicarbonate channel expressed in epithelial cells, and follow the diagnosis criteria. "In a cystic fibrosis model, knockdown of ATF6α was shown to increase delivery of the poorly folded △F508 variant of the cystic fibrosis transmembrane conductance regulator to the plasma membrane where it could function." (PMID 27435960, 2016). "ATF6 plays a major role in transcriptional repression of endogenous cystic fibrosis transmembrane conductance regulator (CFTR) under endoplasmic reticulum stress and is thought to be a potential therapeutic target for cystic fibrosis." (PMID 25241909, 2014).
diabetic retinopathy (3 papers, 2015 to 2025). "In particular, ER stress within normal and disease contexts (e.g., drug exposure, genetic loss of ER transmembrane protein, diabetic retinopathy) resulted in increased ATF6 expression in Müller glial and retinal ganglion cells." (PMID 26063662, 2015). "The optoenergetic activation of mt-EcGAPR suppresses the ER stress–ATF6–pyroptosis axis caused by mitochondrial dysfunction, positioning it as a promising therapeutic agent for not only glaucoma but also other retinal neurodegenerative diseases, such as diabetic retinopathy." (PMID 41162360, 2025).
inflammatory bowel disease (3 papers, 2017 to 2023). A spectrum of small and large bowel inflammatory diseases of unknown etiology. "In the cellular model of inflammatory bowel diseases, ATF6 increases expression of inflammatory cytokines CXCL1 and tumor necrosis factor (TNF) in response to ER stress." (PMID 38007457, 2023). "Overall, ATF6 acts as an important mediator in inflammatory bowel disease pathogenesis connecting the complicated networks of an UPR, ER stress, and autophagy." (PMID 37407995, 2023). "Under inflammatory bowel disease conditions, ER stress-induced unfolded protein response (i.e., activated ATF6) enhances an acute response in the liver, prolonging inflammation." (PMID 29160807, 2017).
injury (3 papers, 2020 to 2023). Damage inflicted on the body as the direct or indirect result of an external force, with or without disruption of structural continuity. "The impact of silencing ATF6 and RIP3 on hepatocyte necroptosis in a hepatocyte model of ER stress and a mouse model of acute liver injury was examined." (PMID 34778458, 2021).
ischemic heart disease (3 papers, 2018 to 2021). "Grp78 and Cat were also increased in hearts from patients with ischemic heart disease, supporting the relevance of the ATF6 adaptive arm of the UPR in human pathology and validating the phenotypes observed in this mouse model of AMI." (PMID 30643122, 2019). "Overexpression of the active ATF6 transcription factor in the heart also has been shown to improve cardiac performance in mouse models of ischemic heart disease, through a mechanism involving ATF6-dependent regulation of the antioxidant gene, catalase." (PMID 30084354, 2018).
lymphoma (3 papers, 2021 to 2024). A malignant (clonal) proliferation of B- lymphocytes or T- lymphocytes which involves the lymph nodes, bone marrow and/or extranodal sites. "Compared with WT group and KO group, the expression levels of p-PERK, p-IRE1α and ATF6 were significantly upregulated in WT + lymphoma cell group, indicating that lymphoma cells can simultaneously activate the three oxidative stress pathways." (PMID 38261741, 2024). "Despite the fact that the wild-type and mutant BMLF1 proteins may have differential effects on the grp78p activation in lymphoma cells and in 293T cells, our results clearly demonstrate that ATF6 acts as an important mediator." (PMID 33919712, 2021). "Lymphoma cells enhanced the expression of p-PERK, p-IRE1α, ATF6, IL-6, IL-4, p-AKT, CD9, CD63 and PD-L1 in bone marrow-derived macrophages by mediating the Notch-1 signaling pathway." (PMID 38261741, 2024). "RAS-driven lymphoma cell lines actually downregulated XBP1, ATF6α, and HSP-α5." (PMID 34399819, 2021).
nonalcoholic fatty liver disease (3 papers, 2023 to 2024). "MiR-149 controls non-alcoholic fatty liver disease by targeting FGF-21; it also inhibits the ATF6 pathway to reduce inflammation and apoptosis in nonalcoholic fatty liver disease brought on by endoplasmic reticulum stress." (PMID 37259030, 2023).
prion disease (3 papers, 2017 to 2021). A transmissible disease that is caused by a protein that is able to induce abnormal folding of normal cellular proteins, leading to characteristic spongiform brain changes, which are associated with neuronal loss without an inflammatory response. "Regarding the results observed in this study, we consider that the IRE1 and ATF6 pathways could be also involved in sporadic prion diseases." (PMID 33466523, 2021). "Mainly PERK but also IRE1α and ATF6 pathways were shown to be involved in the prion disease." (PMID 32854418, 2020). "Different UPR markers such as p-IRE1, active ATF6α, p-PERK and p-eIF2α, BiP and CHOP were found in patients with neurodegenerative diseases including Alzheimer’s, Parkinson’s, Amyloid lateral sclerosis (ALS), prion diseases among others." (PMID 32854418, 2020). "Furthermore, in a cellular model of prion disease, the overexpression of ATF4 or an active mutant form of ATF6 prevented PrP aggregation." (PMID 32854418, 2020).
renal fibrosis (3 papers, 2015 to 2023). A final common manifestation of a wide variety of chronic kidney diseases characterized by glomerulosclerosis and tubulointerstitial fibrosis. "Similar as the studies in CKD patients, renal fibrosis was associated with a sevenfold of Chop upregulation and, importantly, a significant increase for other ER stress markers such as Bip, Perk, Ire-1α and Atf-6 was also noted in UUO-induced mice." (PMID 26247732, 2015). "Excessive hyperglycemia can activate protein kinase RNA-like endoplasmic reticulum kinase (PERK) and transcription factor 6 (ATF6) by upregulating H4R3me2a, promoting EMT and ER stress, accelerating PTEC apoptosis, and aggravating renal fibrosis by upregulating PRMT1 expression." (PMID 36817133, 2023). "In addition, we found that UPR initiators PERK, IRE1α, and ATF6 were activated following AKI, while the expression of XBP1 gradually lowered throughout experiments and inversely correlated with the degree of renal fibrosis." (PMID 35765067, 2022). "It was interestingly noted that loss of Chop significantly inhibited UUO-induced ER stress as manifested by the reduced expression of Bip, Perk, Ire-1α and Atf-6, which further supports the implication of CHOP-related ER stress in the development of renal fibrosis." (PMID 26247732, 2015).
tauopathy (3 papers, 2019 to 2024). Neurodegenerative disorders involving deposition of abnormal tau protein isoforms (tau proteins) in neurons and glial cells in the brain. "From this analysis, we nominated multiple genetic modifiers of tauopathy associated with XBP-1s/ATF6 in C. elegans, including csp-1, dnj-28, hsp-4, ckb-2, and lipl-3." (PMID 39060347, 2024). "XBP-1s promotes clearance of pathological tau, and loss of function of the ATF-6 branch of the UPRER prevents XBP-1s rescue of tauopathy in C. elegans." (PMID 39060347, 2024). "Because xbp-1s-mediated tauopathy behavioral suppression requires atf-6, we also measured atf-6 loss of function effects on total tau protein by immunoblot in Tau (high) animals using two independent atf-6 loss of function alleles." (PMID 31570707, 2019). "Surprisingly, we found atf-6 loss of function completely blocked xbp-1s-mediated tauopathy suppression in Tau (high); xbp-1s Tg; atf-6 (−/−) animals." (PMID 31570707, 2019). "In contrast, we have shown atf-6 loss of function completely abolished xbp-1s-mediated tauopathy suppression in C. elegans." (PMID 31570707, 2019). "Our results show both atf-6 and xbp-1 loss of function enhance tauopathy-induced behavior defects in C. elegans, with xbp-1 loss of function additionally increasing tau protein levels and neurodegeneration." (PMID 31570707, 2019). "To understand whether the other two UPRER branches participate in xbp-1s-mediated tauopathy suppression in C. elegans, we again utilized pek-1 and atf-6 loss of function mutant strains." (PMID 31570707, 2019). "Regardless, the parallel findings for atf-6 and pek-1 loss of function suggests full UPRER functionality promotes xbp-1s-mediated tauopathy suppression in C. elegans." (PMID 31570707, 2019). "This demonstrates an absolute requirement for ATF-6 in mediating tauopathy suppression by transgenic constitutively active XBP-1s expression in C. elegans and a previously unappreciated critical crosstalk between ATF-6 and XBP-1 branches of the UPRER in tau proteostasis." (PMID 31570707, 2019). "Intriguingly, we identified chronic activation of the PERK and ATF6 branches of the UPR induced by Tau35, which has also been found in human tauopathy." (PMID 30606258, 2019). "Given the known importance of the XBP-1 and ATF-6 branches in UPRER transcriptional regulation, a plausible mechanism of tauopathy suppression involves regulation of specific target gene(s) coordinately upregulated by ATF-6n and XBP-1s transcription factors." (PMID 31570707, 2019). "However, both ATF6 and PERK branches of the UPRER participate in amelioration of tauopathy by constitutively active XBP-1, possibly through endoplasmic reticulum-associated protein degradation (ERAD)." (PMID 31570707, 2019). "In contrast, Tau (high); xbp-1s Tg; atf-6 (−/−) animals accumulated total tau protein similar to the level seen in Tau (high) animals, indicating functional ATF-6 is necessary for xbp-1s-mediated tauopathy detoxification." (PMID 31570707, 2019). "Taken together with the requirement for ATF-6 function in XBP-1s-mediated tauopathy suppression, we hypothesize these two transcription factors also form heterodimers in C. elegans to promote tauopathy suppression." (PMID 31570707, 2019).
Type 1 diabetes (3 papers, 2017 to 2025). "However, early-onset juvenile diabetes arises with the loss of MANF in mice and humans, but not in Atf6–/– mice, and has not been reported in patients carrying ATF6 loss-of-function variants." (PMID 39570676, 2025).
Wolfram syndrome (3 papers, 2021 to 2025). Wolfram syndrome (WS) also known as DIDMOAD, is a neurodegenerative disorder characterized by type I diabetes mellitus (DM), diabetes insipidus (DI), sensorineural deafness (D), bilateral optical atrophy (OA) and neurological signs. "Therefore, we propose that ATF6 inactivation causes a syndrome in patients with phenotypic (blindness-deafness) and cellular (photoreceptor–hair cell) features that resemble Usher syndrome, combined with molecular pathomechanisms (ER stress, UPR dysregulation) that are causal in Wolfram syndrome." (PMID 39570676, 2025). "In patients with Wolfram syndrome, because of the variation of WFS1, ATF6 is hyperactivated, leading to dysregulated ATF6 signaling pathway." (PMID 37185285, 2023).
acute pancreatitis (2 papers, 2019 to 2024). An acute inflammatory process that leads to necrosis of the pancreatic parenchyma. "In addition, the increase in ATF6 expression was related to the increase of apoptosis, ER, and mitochondrial diseases in pancreatic tissues of patients with acute pancreatitis and PRSS1 mice." (PMID 38896161, 2024).
adenoma (2 papers, 2018 to 2025). A neoplasm arising from the epithelium. "In our ATF6 transgenic mouse model (nATF6IEC), we previously established a causal role of the microbiota in adenoma formation." (PMID 40890536, 2025). "As atypia became more severe, the level of ATF6 expression increased; the median ATF6-IHC score was 2.0 (range, 0–4) in adenoma with moderate atypia, 5.0 (range, 0–8) in adenoma with severe atypia, and 7.0 (range, 3–14) in pTis cancer." (PMID 28884228, 2018). "ATF6 expression was detectable in all CRCs but not in normal colonic mucosa, was elevated with increase in cellular atypia (adenoma with moderate atypia < severe atypia < pTis CRC, p < 0.001), and higher in dysplasia and CRC than in non-neoplastic colitis (p < 0.001)." (PMID 28884228, 2018).
aneurysm (2 papers, 2023 to 2024). Bulging or ballooning in an area of an artery secondary to arterial wall weakening. "Thoracic aneurysm SMCs shared TFs with thoracic aorta SMCs, such as Zeb1 and Atf6, which are not shared with abdominal aorta or aneurysm SMCs, suggesting these TFs may induce anatomic location-specific signals." (PMID 39590192, 2024).
Arthritis (2 papers, 2022 to 2025). Inflammation of a joint. "BIRC3 is a direct target of ATF6α, and model mice with ATF6α deficiency exhibit reduced arthritis progression, resulting in significant reductions in clinical and pro-inflammatory markers in the joints." (PMID 41291434, 2025). "CIA models were established in mice with ATF6α deficiency, and the incidence and severity of arthritis were significantly lower in ATF6α-/- mice than in ATF6α wild-type (WT) littermates." (PMID 36300114, 2022). "Collectively, these findings indicate that ablation of the ATF6α effectively prevents synovial proliferation and its destruction of the joints, thereby inhibiting the progression of experimental arthritis." (PMID 36300114, 2022). "We measured multiple parameters (i.e., clinical arthritis scores, joint tissue inflammation/destruction, serum levels of proinflammatory cytokines) in vivo experiments, and the results clearly showed that ATF6α is required for the CIA progression, as mice lacking ATF6α were protective against CIA." (PMID 36300114, 2022).
astrocytoma (2 papers, 2020 to 2021). "An increase of full-length ATF6 protein was detected at late time points in neurotropic TBEV Neudoerfl infection of astrocytoma cells and throughout the course of LGTV infection of intestinal cells." (PMID 34834970, 2021).
Blindness (2 papers, 2021 to 2025). Blindness is the condition of lacking visual perception defined as a profound reduction in visual perception. "This combination of auditory and visual dysfunction, along with the biallelic inheritance of ATF6 variants, mirrors Usher syndrome, characterized by blindness, deafness, and autosomal recessive inheritance." (PMID 39570676, 2025). "Furthermore, they support the idea that ATF6 inactivation in people causes progressive sensorineural hearing loss as part of a blindness-deafness genetic syndrome targeting hair cells and cone photoreceptors." (PMID 39570676, 2025).
brain infarcts (2 papers, 2015 to 2021). "Taurine not only caused neuroprotection through the ATF6 and IRE1 pathways, but also reduces apoptosis and cerebral infarction volume in these model." (PMID 34408630, 2021).